AHR (aryl hydrocarbon receptor)
Diseases named in the same sentence as AHR in open-access papers (continued):
Sharing a sentence is not in itself a finding about the gene and the disease.
autoimmune disease (continued). "Depending on the pattern of regulatory transcriptional factors such as SOX5, AHR and NFkB, the polarization of autoimmune diseases progresses in host cell differentiation and maturation." (PMID 36986457, 2023). "Increases in AHR expression are seen in autoimmune diseases and various forms of cancer, and AHR is frequently overexpressed in pancreatic cancer." (PMID 37685961, 2023). "As this field of study has continued to grow, it has become apparent that the AHR is an important novel target for cancer, metabolic diseases, skin conditions, and autoimmune disease." (PMID 36982624, 2023). "Epigenetic regulation of AHR transcription is not only important in different cancers but has also been described for autoimmune disease." (PMID 37696456, 2023). "The aryl hydrocarbon receptor (AhR) is a critical regulator of the pathogenesis of autoimmune disorders." (PMID 37382269, 2023). "AhR plays an important role in regulating the differentiation between Treg cells and Th17 cells, which are pivotal in autoimmune diseases." (PMID 37747052, 2023). "Recently, it has been found that AhR has important functions in innate and adaptive immune response, autoimmune diseases, infection and inflammation." (PMID 35185907, 2022). "AhR contributes to many autoimmune diseases, and this review focuses on outlining the role of AhR in the development of different subtypes of immune cells and SLE." (PMID 36110860, 2022). "By elucidating the role of AhR in autoimmune diseases, researchers can enhance their understanding of the pathogenesis of autoimmune diseases and develop new therapeutic targets." (PMID 36110860, 2022). "It is well known that AhR activation plays a critical role in both autoimmune diseases as well as various types of cancer, including head and neck cancer, where it promotes the migration and proliferation of tumor cells." (PMID 36143966, 2022). "Some studies have been addressed that indoles and alkaloids can attenuate experimental models of autoimmune diseases by the AhR-dependent induction of Tregs." (PMID 35308285, 2022). "A large body of evidence support a prominent role for AHR in the tolerogenic phenotype and progression of inflammatory and autoimmune diseases." (PMID 36499247, 2022). "For this review, we focused on the role of AhR in the development of autoimmune diseases, mainly SLE, in order to provide clues for more effective and targeted prevention and treatment methods." (PMID 36110860, 2022). "In particular, AhR is essential for maintaining the balance between Th17 and Treg cells, which plays a major role in autoimmune diseases, and also controls the differentiation and activity of specific T-cell subsets." (PMID 36110860, 2022). "Previous studies have demonstrated that AhR activation induces functional Tregs, which suppress the development of experimental transplant and autoimmune diseases." (PMID 35461286, 2022). "The aryl hydrocarbon receptor (AHR) signaling pathway participates in immune regulation of multiple autoimmune diseases, including rheumatoid arthritis (RA)." (PMID 35309329, 2022). "AhR is a ligand-activated transcription factor that plays critical roles in various autoimmune diseases, including the regulation of Th17/Treg response." (PMID 35185872, 2022). "In the studies available to date, most of the evidence suggest that AhR activation suppresses inflammatory responses and alleviates autoimmune diseases." (PMID 36110860, 2022). "For example, AHR activation by TCDD or related chemicals in the fetus has been linked to increased risk for eczema, autoimmune diseases, neurodevelopmental disorders and impairment of mammary gland differentiation, as well as others." (PMID 34318329, 2021). "Because the Kyn-AHR axis has an effect on the proliferation of Tregs, it has been considered a potential therapeutic target for the treatment of autoimmune disorder." (PMID 34305913, 2021).
autoimmune disease (continued). "In another autoimmune disease, AhR agonists have been effective in plaque psoriasis on a Phase 2, randomized dose-finding study." (PMID 34512345, 2021). "In many autoimmune diseases, AhR activation is the crucial factor regulating the differentiation of Th17 and Treg cells." (PMID 33013906, 2020). "Such a regulatory role on the T-cell compartment underpins the AhR potential as a therapeutic target for the treatment of autoimmune disorders." (PMID 32635461, 2020). "Environmental factors contribute to autoimmune disease manifestation, and as regarded today, AhR has become an important factor in studies of immunomodulation." (PMID 32899152, 2020). "One dietary component that has been shown to modulate autoimmune disease development is ligands that activate the aryl hydrocarbon receptor (AhR)." (PMID 33552063, 2020). "In accordance with that environmental factors undoubtedly contribute to autoimmune disease manifestation, and as regarded today, AhR has become an essential factor in studies of immunomodulation." (PMID 32899152, 2020). "In the aspect of autoimmune diseases, AhR upregulation and modulation toward increased Treg cell ratio seems to ameliorate of inflammation and inhibit autoimmune response." (PMID 32899152, 2020). "According to the type of ligand, activation of AhR can induce Th17 or Treg cell differentiation, leading to aggravation of proinflammatory or immunosuppressive responses, respectively, in autoimmune diseases." (PMID 33013906, 2020). "The differential effects of different AHR agonists on autoimmune disease progression is probably due to their influence on the T helper responses responsible for the disease progression." (PMID 31001262, 2019). "The fact that AHR can act on T helper responses suggested its effects in the development of inflammatory and autoimmune diseases." (PMID 31001262, 2019). "This suggest a link to environmental factors containing ligands of AHR that influence autoimmune disease." (PMID 31001262, 2019). "C2 represents a novel selective AHR modulator with considerable structural similarities to the AHR agonist LAQ that is currently under study as a therapeutic option for autoimmune disorders." (PMID 30893768, 2019). "AHR is critical in maintaining the balance between Th17 and Treg cells which play a major role in autoimmune disease." (PMID 30574142, 2018). "Cumulatively, these data demonstrate a clear role of AHR in autoimmune disease and indicate a likely role of AHR ligands present in PM in autoimmune disease." (PMID 30574142, 2018). "In the context of autoimmune disease, AHR has been shown to play a role in T1D, RA, MS, and SLE by altering T cell functions." (PMID 30574142, 2018). "Recently, it was shown that the intact SRM1649b PM enhanced Th17 differentiation in an AHR-dependent manner, but using a murine model of autoimmune disease, was shown to reduce pathologic T cells in the CNS in vivo." (PMID 30576387, 2018). "The AHR plays a critical role in the balance of effector and regulatory T cells and in autoimmune disease." (PMID 30574142, 2018). "The AHR responds to several environmental toxicants found in PM, such as PAHs, and PM exposures alter T cell balance and autoimmune disease via the AHR." (PMID 30574142, 2018). "Currently, the focus is on understanding how PAHs present in PM act through the AHR to shift the T cell balance and alter autoimmune disease states." (PMID 30574142, 2018). "Given the complexity of AHR signaling and the differential regulation of T cells, the AHR has been studied as a candidate target for autoimmune disease." (PMID 30574142, 2018). "We examine the data demonstrating the effects of organic constituents adhered to PM, specifically AHR ligands, on T cells and suggest the AHR pathway as a target for modulating PM-mediated autoimmune disease." (PMID 30574142, 2018). "We then focus on the AHR as the receptor central to the mechanism behind modulating T cell responses in PM-mediated autoimmune disease." (PMID 30574142, 2018).
autoimmune disease (continued). "This review examines the current literature on the effects of atmospheric particulate matter (PM) on autoimmune disease and proposes a new role for the aryl hydrocarbon receptor (AHR) as a modulator of T cells in PM-mediated autoimmune disease." (PMID 30574142, 2018). "Together these data imply a role of early environmental exposure with AHR-mediated autoimmune disease." (PMID 30574142, 2018). "Several studies have found that the AHR modulates the balance between regulatory and effector T cell functions and drives T cell differentiation in vitro and in vivo using murine models of autoimmune disease." (PMID 30574142, 2018). "The transcription factor aryl hydrocarbon receptor (AHR) regulates the generation of Th17 cells, CD4 T cells linked the development of autoimmune diseases." (PMID 29884199, 2018). "This review focuses on the AHR as a potential mechanistic target for modulating T cell responses associated with PM-mediated autoimmune disease providing the most up-to-date literature on the role of AHR in autoreactive T cell function and autoimmune disease." (PMID 30574142, 2018). "Several naturally occurring ligands of AhR, including indoles, reportedly ameliorated autoimmune diseases such as EAE or allergic asthma." (PMID 28666018, 2017). "Development of the aryl hydrocarbon receptor as a viable target for clinical drugs, especially for cancer and autoimmune diseases, hinges on the identification of ligands with significant AhR-dependent effects in model systems." (PMID 28424418, 2017). "Therefore, our study indicates that the modulation of AHR transcription by a promoter variant has a profound influence on vitiligo, not only advancing our understanding on AHR function but also providing novel insight into the pathogenesis of degenerative or autoimmune diseases including vitiligo." (PMID 26370050, 2015). "Aryl hydrocarbon receptor and tryptophan metabolites participate in experimental models of autoimmune diseases." (PMID 25400638, 2014). "Since that time, there has been a flood of reports on the role of the AHR in the adaptive immune system and animal models of disease, particularly autoimmune disease." (PMID 25324842, 2014). "Aryl hydrocarbon receptors (AhR) are involved with regulating immune responses and the development of TH-17 cells, which are key effector T cells in a variety of human autoimmune diseases." (PMID 24804084, 2014). "The aim of the review is to discuss how the AhR signaling pathway is involved in the process of autoimmune disease and immune regulatory effects on inflammation mediated by CD4 helper T cell subsets." (PMID 24905409, 2014). "Specific to the role of environmental factors in autoimmune disease etiology, there has been an improved understanding of the role of specific signaling molecules (e.g., TLRs, AhR)." (PMID 25196523, 2014). "In models of autoimmune diseases such as experimental autoimmune encephalomyelitis (EAE) it became evident that the aryl hydrocarbon receptor (AHR) plays an important role in regulation of the immune response." (PMID 24692846, 2014). "The role of AhR in clinical autoimmune disease is a novel area of research and expression of AhR on PBMCs obtained from active BD patients has, to our knowledge, not yet been addressed before." (PMID 25045206, 2014). "Many recent studies have suggested that activation of the aryl hydrocarbon receptor (AhR) reduces immune responses, thus suppressing allergies and autoimmune diseases." (PMID 24747651, 2014). "In addition to its homeostatic functions, the AhR has been identified as a candidate therapeutic target in multiple autoimmune diseases." (PMID 41321307, 2025). "The aryl hydrocarbon receptor (AHR), involved in autoimmune diseases, may be implicated in migraine, though its role remains unclear." (PMID 40542608, 2025). "The AhR plays a key role in affecting immune responses in autoimmune diseases." (PMID 38509264, 2024).
autoimmune disease (continued). "Theoretically, strategies to enhance AHR activity may be clinically applied for the treatment of several types of inflammatory and autoimmune diseases, whereas inhibiting AHR may be considered for cancer therapy." (PMID 37394584, 2023). "The role of AHR in the differentiation of T cell subpopulations such as IL-17-expressing T helper cells (Th17) and regulatory T cells (Treg) and its significance for autoimmune disease has been established." (PMID 37696456, 2023). "In various autoimmune diseases, AhR activation regulates the differentiation of Th cells." (PMID 37382269, 2023). "Thus, AhR is considered to play an important role in the inflammation response and the occurrence and development of autoimmune disorders." (PMID 37382269, 2023). "There is a paucity of evidence showing mutations of IDO1 and AHR genes that are linked to a direct cause-and-effect relationship with autoimmune diseases; however, functional defects of IDO1 caused by various factors are observed in autoimmune diseases." (PMID 37394584, 2023). "By contrast, AhR-induced tolDCs could be considered powerful tools for immunotherapy, particularly in the context of autoimmune diseases." (PMID 37175508, 2023). "Our study demonstrates a newly emerging role for AHR in mediating the interdependence between T lymphocytes and the microbiota, while simultaneously identifying new potential molecular targets for the treatment of MS and other autoimmune diseases." (PMID 36787309, 2023). "Overall, chronic consumption of phytochemicals in Vicia faba L. and their gut biotransformation may protect against autoimmune disease pathogenesis by AhR modulation." (PMID 35308285, 2022). "However, there is still much evidence that ligand activation of AhR improves SLE symptoms, such as I3C and resveratrol, which suggests that AhR is a promising therapeutic target for autoimmune diseases." (PMID 36110860, 2022). "Their recent findings suggest that the GLK-induced AhR-ROR-γt complex in Th17 may serve as a marker of IL-17A-mediated autoimmune disease and could be a new therapeutic target for human SLE and several diseases." (PMID 36110860, 2022). "Also, it will help researchers to understand the role of AhR in regulating immune responses in autoimmune diseases, cancers, metabolic syndromes, and infectious diseases." (PMID 36601108, 2022). "The recruitment of AhR at different target sites can subsequently alter the biological and cellular processes, including the immune responses in allergic diseases, cancers, and autoimmune diseases." (PMID 36601108, 2022). "RA is a common autoimmune disease and AHR plays a role in regulating the response to the environment factors and may contribute to disease development." (PMID 35309329, 2022). "Moreover, various models of inflammatory and autoimmune diseases have revealed that activation of AHR in vivo by TCDD suppresses allergic responses and immune lung diseases as well as multiple sclerosis and diabetes." (PMID 36499247, 2022). "The emerging role of the aryl hydrocarbon receptor (AhR) receptor pathway in the human gut for the generation of T regulatory cells (Tregs) in the etiopathogenesis of autoimmune diseases suggests that broad beans might benefit these types of diseases." (PMID 35308285, 2022). "Therefore, targeting the AhR signaling has been suggested as a promised approach for autoimmune disease management." (PMID 35308285, 2022). "Moreover, though AhR is unnecessary for Th17 differentiation, its activation promotes further function and differentiation of Th17, leading to the development of various autoimmune diseases dependent on Th17 cells." (PMID 36110860, 2022). "According to the previous section, we have learned that AhR is essential for immune function, and its role in autoimmunity is mainly achieved by regulating the differentiation and function of multiple immune cells, thus affecting autoimmune diseases." (PMID 36110860, 2022).
autoimmune disease (continued). "Interestingly, some research studies found that AhR activation by agonist such as 6-formylindolo [3,2-b] carbazole interfered with the Treg development and increased the severity of autoimmune disease." (PMID 34512345, 2021). "Notably, its high relevance in the immune response of vertebrates, as well as the involvement in the onset of pathological conditions, e.g., cancer and autoimmune diseases, makes the AhR a promising target for drug development and host-directed therapy (HDT)." (PMID 33668313, 2021). "In fact, when activated, AhR is capable of inhibiting the production of several proinflammatory cytokines and of controlling the generation of regulatory T (Treg) cells and/or T helper 17 (Th17) cells in mouse models of autoimmune diseases." (PMID 34065885, 2021). "Besides, several studies have shown that AhR-induced miR-212/132 cluster suppresses cancers, attenuates autoimmune diseases, and has an anti-inflammatory role in different immune responses by regulating cytokine levels and immune cells." (PMID 34746229, 2021). "Further analysis of the literature shows an association of selected microRNAs with autoimmune diseases, however, they have not been studied in the context of interactions with AhR in these particular entities." (PMID 32899152, 2020). "Therefore, AhR is considered a potential target for new therapeutic strategies in autoimmune diseases." (PMID 32899152, 2020). "Thus, identification of FoxP3 as a marker and master regulator of Tregs established the possible link between AhR and the regulation of inflammation and autoimmune disease." (PMID 33105907, 2020). "However to date, in the aspect of autoimmune diseases, there is still a paucity data regarding the regulation of AhR by miRNA." (PMID 32899152, 2020). "By binding diverse dietary, cellular, and microbe-derived ligands, AhR might be involved in autoimmune diseases via the transduction of extrinsic and intrinsic signals into cellular responses." (PMID 31772949, 2019). "Here, we investigated whether GLK-induced AhR–ROR-γt signaling in T cells is a therapeutic target for human autoimmune diseases such as SLE." (PMID 31318609, 2019). "Further studies investigating the role of AHR beyond TH17 differentiation may provide a useful understanding of the physiopathology of autoimmune diseases." (PMID 30425241, 2018). "The data presented here shed light on some important questions and support the hypothesis that ligands of the AHR found in PM can aggravate autoimmune disease after inhalation." (PMID 30143013, 2018). "The identification of components of PM that activate the AHR and also specific AHR pathway targets that can shift the immune balance from inflammatory to regulatory are crucial for understanding the mechanisms through which the AHR contributes to PM-mediated autoimmune disease." (PMID 30574142, 2018). "FOXP3+ Tregs are also modulated by AHR and play a role in autoimmune disease." (PMID 30574142, 2018). "We propose a novel hypothesis that AHR ligands present in atmospheric PM activate the AHR shifting the T cell balance from regulatory to effector ultimately leading to PM-mediated autoimmune disease." (PMID 30574142, 2018). "Additionally, PM exposures act through the AHR altering T cell responses in vitro and in vivo changing autoimmune disease pathology." (PMID 30574142, 2018). "However, the activation of AhR is related to differentiation of regulatory T cells and suppression of autoimmune disease." (PMID 30090104, 2018). "Further studies investigating the mechanisms by which AHR mediates a potential pathogenicity in TH17 cells may provide a useful understanding of the physiopathology of autoimmune diseases." (PMID 30425241, 2018). "Our results suggest that AHR activation in Th17 cells might be a convergent mechanism by which different environmental pollutants aggravate autoimmune diseases." (PMID 29884199, 2018).